ZC2HC1C (zinc finger C2HC-type containing 1C)
Synonyms: C14orf140; FAM164C
Tractability: No criterion of Open Targets' tractability assessment is met for any kind of drug.
Gene: Protein-coding gene on chromosome 14 (75,064,109 to 75,119,502, forward strand). Ensembl gene ENSG00000119703.
Subcellular location (Human Protein Atlas): Nuclear speckles; Mitochondria
Gene Ontology:
Molecular function: protein binding
Genetic constraint (gnomAD): Loss-of-function variants: 25 observed, 41.46 expected, observed/expected ratio (o/e) 0.6, 90% interval 0.44 to 0.84. The upper end of that interval is the gene's LOEUF score, 0.84, which puts it in group 3 of 6, group 1 being the genes least tolerant of losing a copy. Missense variants: 519 observed, 578.22 expected, observed/expected ratio (o/e) 0.9, 90% interval 0.83 to 0.96. Synonymous variants: 209 observed, 227.21 expected, observed/expected ratio (o/e) 0.92, 90% interval 0.82 to 1.03.
Homologues: Orthologues: chimpanzee ZC2HC1C (98% identical), macaque ZC2HC1C (90% identical), dog ZC2HC1C (74% identical), pig ZC2HC1C (73% identical), guinea pig ZC2HC1C (66% identical), rat Zc2hc1c (63% identical), mouse Zc2hc1c (62% identical), rabbit ZC2HC1C (61% identical), tropical clawed frog zc2hc1c (25% identical), zebrafish zc2hc1c (16% identical).
Diseases named in the same sentence as ZC2HC1C in open-access papers:
ZC2HC1C is named in the same sentence as 3 diseases in open-access papers, as found by Europe PMC text mining. Sharing a sentence is not in itself a finding about the gene and the disease. The quoted sentences say what the papers report.
Alzheimer disease (1 paper, 2025). A progressive, neurodegenerative disease characterized by loss of function and death of nerve cells in several areas of the brain leading to loss of cognitive function such as memory and language. "Moreover, the construction of a brain region of interest (ROI) guided by an algorithm incorporating structural constraints revealed a plausible diagnostic correlation between ZC2HC1C and Alzheimer’s disease (AD), suggesting its potential as a biomarker." (PMID 40282865, 2025).
autism spectrum disorder (1 paper, 2025). A spectrum of developmental disorders that includes autism, and Asperger syndrome. "In this manuscript, we establish a probable association between the homozygous variant identified within the ZC2HC1C gene and autism spectrum disorder (ASD)." (PMID 40282865, 2025). "Within this framework, the primary aim of the current study is to establish, for the first time, a likely association between an identified homozygous variant within ZC2HC1C (identified by whole-exome sequencing) and a patient affected by autism spectrum disorder (ASD)." (PMID 40282865, 2025).
gastric cancer (1 paper, 2016). A primary or metastatic malignant neoplasm involving the stomach. "The effect of the two novel somatic mutated genes (ZC2HC1C and C15orf57) in gastric cancer requires further investigation." (PMID 27270314, 2016).